IL10 (interleukin 10)
Diseases named in the same sentence as IL10 in open-access papers (continued):
Sharing a sentence is not in itself a finding about the gene and the disease.
liver fibrosis (continued). "In a subgroup of patients with advanced liver fibrosis, SLD was linked with lower serum concentrations of IL-4, IL-5, IL-9, IL-10, IL-13 and IL-22 and higher concentrations of HGH and VEGF." (PMID 39200991, 2024). "The improvement of liver fibrosis after DAA treatment was associated with higher baseline values of platelet count as well as TNF-α and IL-10 genetic polymorphisms." (PMID 36674897, 2023). "MSCs can also secrete anti-inflammatory cytokines, such as IL-4 and IL-10, to regulate inflammatory response and reduce liver fibrosis." (PMID 36644008, 2023). "Exogenous IL-10 was shown to reverse CCl4-induced hepatic fibrosis by reducing the production of TGF-β1, MMP-2, and TIMP-1 in a rat model, demonstrating that IL-10 has antifibrotic effects via inhibiting HSC activity." (PMID 36826975, 2023). "In the mouse model of liver fibrosis induced by CCL4, BM-MSCs were injected into the injured liver of mice, which significantly reduced the level of IL-17 and increased the level of IL-10, and alleviated the degree of liver fibrosis." (PMID 36644008, 2023). "The frequency of patients with the TT genotype for IL-10-1082 T/C and the GG genotype for IL-10-592 G/T was higher for those whose liver fibrosis improved." (PMID 36674897, 2023). "IL-10 is an anti-inflammatory cytokine that plays important roles in regulating hepatic inflammation, cell necrosis, apoptosis, and liver fibrosis and in stimulating liver regeneration after injury." (PMID 36428795, 2022). "Studies have shown that the remission of liver fibrosis after huMSCs infusion is attributed to the conversion of M1 macrophages to M2 macrophages, with M2 secreting IL-10 and subsequently increasing M1 macrophage apoptosis." (PMID 35895169, 2022). "In the same way, transplantation of HLCs eliminated CCl4-induced liver fibrosis and conserved the function of the liver via the release of transforming growth factors β 1, IL-6, and IL-10." (PMID 35765490, 2022). "Using the CCl4‐induced experimental mouse model of chronic liver damage, we demonstrated that repeated intrahepatic administrations of Ad‐IL10 mixed with CMC effectively mitigated the development of hepatic fibrosis." (PMID 36176604, 2022). "CD4+ T cells activity mediates the progression of liver fibrosis by intrinsic apoptosis, by secreting signature cytokines IL-4, IL-10, and IFN-γ, and by stimulating other immune cells such as NK cells." (PMID 35903097, 2022). "In our proof‐of‐principle study using the CCl4‐induced experimental mouse model of chronic liver damage, we showed that repeated intrahepatic administrations of Ad‐IL10 mixed with CMC effectively alleviated the development of hepatic fibrosis." (PMID 36176604, 2022). "In our proof‐of‐principle experiment using the CCl4‐induced experimental mouse model of chronic liver damage, we demonstrated that repeated intrahepatic administrations of Ad‐IL10 mixed with CMC effectively mitigated the development of hepatic fibrosis." (PMID 36176604, 2022). "Cytokines IL-10 and IL-13 are considered as anti-inflammatory and upregulated in acute liver injury and liver fibrosis to prevent the damage." (PMID 33679236, 2021).
liver fibrosis (continued). "Hepatocytes produce IL-10 which downregulates pro-inflammatory responses and has a potential modulatory effect on liver fibrosis." (PMID 33841164, 2021). "The increase of α-SMA and NF-κB in HSCs was attenuated by ectogenic IL-10 in CCl4-induced liver fibrosis." (PMID 33841164, 2021). "IL-10 gene therapy attenuated hepatic fibrosis and prevented cell apoptosis in a thioacetamide-treated liver." (PMID 33841164, 2021). "In CCl4-induced liver fibrosis mice, intravenously injected mouse BM-MSCs successfully migrated to the damaged liver and significantly relieved liver fibrosis by decreasing IL-17 and increasing IL-10." (PMID 34829827, 2021). "On the other hand, high levels of IL-10 were shown to lead to an impairment in cytotoxic response, decreased inflammatory response and progression to liver fibrosis." (PMID 33717024, 2021). "IL10 has a central role in chronic hepatitis C, limiting the inflammatory response and reducing liver fibrosis." (PMID 34497613, 2021). "Further study is warranted on the impact of IL-10 produced by immune cells in adipose tissue under TN conditions on liver fibrosis." (PMID 34124102, 2021). "IL-10 is widely known as a representative anti-inflammatory factor that regulates pro-inflammatory mediators contributing to liver fibrosis." (PMID 32746905, 2020). "IL10-KO mice show increased neutrophil infiltration and hepatic fibrosis during repeated CCl4 administration." (PMID 32373617, 2020). "IL-10 is also known to play a key role in liver fibrosis by promoting apoptosis of hepatic satellite cells (HSCs) and regulating their function." (PMID 32746905, 2020). "The significant associations of advanced liver fibrosis with higher levels of IL-6, IFN-γ, IL-10, and GM-CSF, despite being insignificant upon Bonferroni correction, are in accordance with some previous studies and are worthy of further investigation." (PMID 33348839, 2020). "This study evaluated interleukin 10 (IL10) expression in the liver and plasma of 45 HCV patients and its association with the pathogenesis and progression of liver fibrosis." (PMID 33125400, 2020). "Remarkably, it is well-known that TGF-β and IL-10 play a major role in chronic inflammation and liver fibrosis." (PMID 32664587, 2020). "Another study including patients with CHB and chronic hepatitis C (CHC) also indicated that Tfr cells possibly modulated liver fibrosis by secreting the regulatory cytokine IL-10 and TGFβ." (PMID 32676074, 2020). "Compared to the untreated liver fibrosis group, the expression of inflammatory factors including IL-1, IL-2, IL-6, IL-8, IL-10, and TNF-α were significantly decreased in the hBM-MSCs and hBM-MSCs-Ex treatment groups (p < 0.05)." (PMID 30885249, 2019). "Previous studies reported that DC-IL10 production of IL-10 is a crucial negative regulator of liver fibrosis." (PMID 30800002, 2019). "In this study, we made a new attempt to deliver IL-10 gene-modified BMDCs into mice with CCl4-induced liver fibrosis to evaluate the immunotherapy effects and explore the molecular mechanisms of DC-IL10 on liver fibrosis." (PMID 30800002, 2019). "Reports on the possible role of IL-10 (secreted by regulatory cells such as regulatory myeloid and/or T cells) in relation to hepatic fibrosis made mention of a regulatory role of the il-10 gene SNPs on the progression of periportal fibrosis." (PMID 30546364, 2018). "In fact, higher risk of severe periportal fibrosis was reported when IL-10 production by blood mononuclear cells from schistosomiasis-diseased patients was low suggesting a protective role of IL-10 against hepatic fibrosis." (PMID 30546364, 2018). "In summary, our in vitro and in vivo findings demonstrated that treatment with EXE attenuates the process of hepatic fibrosis by inhibiting the activation of HSCs and upregulating the secretion of IL-10." (PMID 29464186, 2017). "It has been shown that the severity of fibrosis is increased in carbon tetrachloride-induced liver fibrosis in IL-10 KO mice." (PMID 27314021, 2016).
liver fibrosis (continued). "The Th-1 immunity profile (IL-2, IL-12, TNF-α, and IFN-γ) is correlated with liver fibrosis in patients with chronic hepatitis C, whereas Th2 immunity profile (IL-4 and IL-10) cannot control viral clearance." (PMID 27413763, 2016). "On the other hand, HCV patients with severe liver fibrosis (F3-4) displayed significant inverse correlation between IL-10 and all other cytokines." (PMID 26742960, 2016). "HCV patients with mild liver fibrosis (F1-2) showed stronger connections between proinflammatory cytokines with a clear positive connection of IL-10 controlling the TNF node." (PMID 26742960, 2016). "There was a clear positive connection of IL-10 with the TNF node in patients with mild liver fibrosis, whereas there is an evident inverse correlation between IL-10 with all other cytokine nodes." (PMID 26742960, 2016). "The analysis of cytokine signatures further underscored that the subgroup of patients with mild liver fibrosis (F1-2) presented relevant frequency of subjects with high IL-10 serum levels as compared to patients with severe liver fibrosis (F3-4)." (PMID 26742960, 2016). "Higher hepatic TNF-α levels and more severe liver fibrosis can be observed in the carbon tetrachloride (CCl4) treated IL-10 KO mice than in the wild type animals." (PMID 26199463, 2015). "Similar to IL-10, elevated level of IL-20 was found in hepatocytes and hepatic stellate cells of patients suffering from liver fibrosis." (PMID 26199463, 2015). "Increased endogenous IL-10 expression ameliorates chronic inflammatory burst and subsequent liver fibrosis after repeated stimulation with CCl4." (PMID 25374445, 2014). "IL-10 is an important Th2 cytokine, which also plays a critical immunoregulatory role in the protection against hepatic fibrosis in human schistosomiasis." (PMID 24598061, 2014). "Previously, we showed that exogenous cytokine IL-10 suppresses liver fibrosis progression induced by CCL4 in rats." (PMID 24993843, 2014). "The aim of the present study was to evaluate the anti-fibrotic effects of the rat interleukin-10 (rIL-10) gene by HBT gene delivery system on experimental liver fibrosis in rats and its possible mechanism." (PMID 24993843, 2014). "IL-10, which is known to modulate hepatic fibrosis, showed only a borderline increase in R5-supernatant treated cells." (PMID 24637780, 2014). "The possible role of BMSC in developing liver fibrosis during liver injury, supposably due to interleukin 10 mediation, has been discussed controversially." (PMID 24312129, 2013). "Increased endogenous IL-10 expression ameliorates acute inflammatory burst and subsequent liver fibrosis after repeated stimulations with CCl4." (PMID 23335984, 2013). "In general, the top canonical pathways included those related to leukocyte extravasation, hepatic fibrosis, eicosanoid signaling, chemokine signaling, IL10 signaling, and the complement system." (PMID 20625511, 2010). "Similarly, the 15 mg/kg dose exhibited greater efficacy, reducing IL-6 and IL-1β levels by 54.62% and 47.06%, respectively, and enhancing IL-10 levels by 227.27% as compared to TAA-induced liver fibrosis group." (PMID 41365955, 2025). "IL-10, which is secreted by Marco+ KCs, is a key anti-inflammatory cytokine for liver fibrosis." (PMID 40651612, 2025). "In a previous study, IL-10 KO mice exposed to chronic carbon tetrachloride developed significantly more liver fibrosis, further supporting that IL-10 may play a role in preventing hepatic fibrosis." (PMID 40643550, 2025). "Moreover, IL-10 gene therapy has been shown to reverse thioacetamide-induced liver fibrosis in mice." (PMID 40248698, 2025). "Regarding cytokines TGF‐β1 and IL‐10, which are associated with MDSCs in lung and liver fibrosis, our measurements showed no significant changes in colonic MDSCs from TNBS‐induced fibrotic mice compared to normal mice." (PMID 39739231, 2025).
liver fibrosis (continued). "HSCs may secrete autocrine IL-10 to inhibit collagen synthesis, suppress liver inflammatory responses, and slow the progression of liver fibrosis." (PMID 39995661, 2025). "In the CCl4 cirrhosis model, liver fibrosis attenuated in the presence of IL-10." (PMID 39596809, 2024). "IL-10 plays an important role in the inhibition of schistosomiasis liver fibrosis." (PMID 37375483, 2023). "Hypertension may induce liver injury and hepatic fibrosis through decreased interleukin-10-mediated or heme oxygenase-1-induced anti-inflammatory mechanisms." (PMID 37749307, 2023). "However, it is worth noting that our cytokine profile findings seem to be different from those seen in schistosomiasis mansoni, which has shown higher levels of IL-9, IL-10 and IL-17 in patients with advanced liver fibrosis." (PMID 37887717, 2023). "Aside from the possible role in tissue repairing, IL-22 and IL-10 may also play an important role in the modulation of liver fibrosis, decreasing HSC activation and tissue inflammation." (PMID 37373379, 2023). "Similarly, Chai et al45 reported an increase in anti-inflammatory cytokines including IL-4 and IL-10 alongside mobilization of liver resident macrophages (Kupffer cells) following administration of MSC in a murine model of liver fibrosis." (PMID 37052348, 2023). "The most sophisticated difference was between the CHC-SF and CHC-NSF groups in the plasma levels of IL-10, which could make this cytokine a useful biomarker of liver fibrosis." (PMID 37569857, 2023). "The secretion of IL-10 by hepatic B-1 cells was significantly increased after schistosome infection, and IL-10 attenuated inflammation and liver fibrosis by decreasing the expression of inflammatory factors and chemokines and inhibiting the infiltration of Ly6chi monocytes in the liver." (PMID 37375483, 2023). "Infected mice treated with ginger Cs Nps 500 mg/kg possessed a lessening in the IL-4 and IL-10 levels, which agreed with the report stating that ginger extract declined the inflammation mediators that have a marked contribution in schistosomal-liver fibrosis and its consequences." (PMID 36362992, 2022). "As a proof‐of‐concept experiment, we sought to investigate whether the intrahepatic administration of CMC‐encapsulated Ad‐IL10 would prevent and/or alleviate hepatic fibrosis in the mouse model of CCl4‐induced experimental hepatic fibrosis." (PMID 36176604, 2022). "IL-10 is a fibrosis-related inflammatory mediator involved in the disease progression of pulmonary fibrosis, renal fibrosis, interstitial fibrosis, cardiac fibrosis, and liver fibrosis." (PMID 36295022, 2022). "It has been reported that IL10 exhibits anti‐hepatic fibrosis activity." (PMID 36176604, 2022). "Another study reported that hepatic fibrosis leads to the accumulation of liver resident IL10+ cells, and that these cells could directly impair CD8+ T cell functions and result in the development of hepatocellular carcinoma." (PMID 35903097, 2022). "IL-10 can be produced by lymphocytes and inhibit liver fibrosis." (PMID 35268138, 2022). "To provide a proof‐of‐concept study, we established a CCl4‐induced experimental mouse model of chronic liver damage, and demonstrated that repeated intrahepatic injections, once every 10 days for up to six times, of Ad‐IL10 mixed with CMC effectively alleviated the development of hepatic fibrosis." (PMID 36176604, 2022). "Another report demonstrated that although IL-10 therapy improves various inflammatory parameters and liver fibrosis in patients with chronic HCV infection, in the long term it may lead to increased HCV burden via alterations in immunologic viral surveillance." (PMID 36148228, 2022). "We examined whether IL-10 could increase the severity liver fibrosis by inducing BAT dysfunction under thermoneutrality." (PMID 34124102, 2021). "We therefore hypothesize that inadequate BAT activity under TN conditions and deletion of IL-10 may accelerate hepatic fibrosis progression." (PMID 34124102, 2021).
liver fibrosis (continued). "Therefore, it is very important to select and study targets capable of blocking pro-inflammatory (IL-13, IL-17, and IL-33) or inducing anti-inflammatory interleukin (IL-10) in the complex process of liver fibrosis." (PMID 33841164, 2021). "The therapeutic effects of DZNep as epigenetic drug in liver fibrosis are associated with the regulation of EZH2 towards direct target genes encoding TGF-β1 pseudoreceptor BAMBI, anti-inflammatory cytokine IL10 and cell cycle regulators CDKN1A, GADD45A and GADD45B, which are also regulated by JMJD3." (PMID 33391480, 2021). "DOP reduced LPS entry into the liver to activate the TLR4/NF-κB signaling pathway, thereby reducing the production of inflammatory factors such as TGF-β and TNF-α, increasing the production of anti-inflammatory factors such as IL-10, and reducing the deposition of collagen to treat liver fibrosis." (PMID 32226380, 2020). "On the other hand, the lack of intrahepatic IL10 mRNA expression by HSCs in association with the induction of collagenase leads to advanced liver fibrosis." (PMID 33125400, 2020). "Additionally, previous studies have reported a protective role for IL-10 in HCV infection in relation to the progression of liver fibrosis." (PMID 33125400, 2020). "The anti-hepatic fibrosis effect of Treg cells is likely to be related to IL-10 secretion." (PMID 31639000, 2019). "The inhibitory activities of DC-IL10 on liver fibrosis might involve their capacity to produce high levels of IL-10 and directly inhibit liver inflammation." (PMID 30800002, 2019). "The plasma level of IL-10 is elevated with IL-6, along with TNF-α and IL-10 in non-fibrotic groups, but low IL-10 levels were associated with moderate/severe hepatic fibrosis - while IL-13 was raised in this group 11." (PMID 31024947, 2019). "Given the evidence above, we believed that IL-10 is a protective factor in liver fibrosis." (PMID 30800002, 2019). "Moreover, expression of Th1 or Th2 cytokines important for liver fibrosis, such as IL-6, IL-10, IL-13, and TNF-α, were also detected in our experiment." (PMID 29703259, 2018). "Surprisingly, we observed a transient reduction in IL‐10 levels on day 5, which contradicts a previous finding by Manuelpillai and colleagues that described an increase in IL‐10 levels following hAEC treatment in a mouse model of liver fibrosis." (PMID 28371562, 2017). "In summary, Treg impairment in number, IL-10 production, and inhibition of T cell proliferation may promote bile duct injury and liver fibrosis in PBC patients." (PMID 29312539, 2017). "In contrast, IL-10 knockout mice showed a more significant liver fibrosis than wild-type mice." (PMID 28646179, 2017). "It was reported that IL-10 might have a crucial role in the progression of liver fibrosis, which was also consistent with our present study." (PMID 29312539, 2017). "In conclusion, our findings demonstrated that HCV infection triggers a local and systemic cytokine ensemble orchestrated by TNF and tuned by IL-10 in such a manner that mirrors the liver fibrosis score, which highly suggests the relevance of these set of biomarkers for clinical investigations." (PMID 26742960, 2016). "The results demonstrated that HCV patients with moderate fibrosis (F1-2) presented high frequency of CD8+ T-cells along with lower levels of proinflammatory cytokines (IL-6 and IFN-γ) but higher IL-10 levels as compared to those patients with severe liver fibrosis (F3-4)." (PMID 26742960, 2016). "In other studies with animal models, it was demonstrated that the absence of IL-10 was associated with liver fibrosis." (PMID 26742960, 2016). "But it was found that IL-10 gene therapy attenuated CCl4 induced liver fibrosis in mice." (PMID 26881046, 2016). "The most studied members of the IL-10 family related to liver fibrosis are IL-10, IL-20, and IL-22." (PMID 26199463, 2015). "Furthermore, IL-10 levels were increased in rats with liver fibrosis that were treated with Panax notoginseng saponins." (PMID 25692549, 2015).